TRPV4 (transient receptor potential cation channel subfamily V member 4)
Diseases named in the same sentence as TRPV4 in open-access papers (continued):
Sharing a sentence is not in itself a finding about the gene and the disease.
diabetes (continued). "We conclude that hyperglycaemia and diabetes reduce the molecular and functional expression of TRPV4 channels in retinal microvascular endothelial cells." (PMID 26047504, 2015). "A final series of experiments was carried out to investigate the effects of diabetes on retinovascular TRPV4 expression in vivo." (PMID 26047504, 2015). "The current findings suggest that diabetes reduced both TRPV4 expression and function in the retinal microcirculation, an important site of microvascular pathology." (PMID 26047504, 2015). "Initially, we investigated whether TRPV4 activation in the DRG of mice with diabetes mellitus produced pain-like responses, oxidative neurotoxicity, and apoptosis." (PMID 38976129, 2024). "Only Trpv4+/+ mice developed mechanical hyperalgesia after the diabetes induction." (PMID 36670886, 2022). "Therefore, this review outlines how the TRPV4 channel represents an innovative target to tackle neuropathic pain signaling in models induced by trauma, surgery, chemotherapy, cancer, diabetes and alcohol intake." (PMID 36670886, 2022). "Apart from cardiovascular diseases, TRPV4 has been found to affect diabetes-related complications." (PMID 33981725, 2021). "Moreover, in blood vessels from animal models of diabetes, reduced TRPV4 expression has been consistently reported across numerous studies." (PMID 34616307, 2021). "Our previous work showed that TRPV4 antagonists have significant therapeutic potential for the control of BRB breakdown in DME since they inhibit excessive permeation in the retina of the streptozotocin preclinical rat model of diabetes." (PMID 31048895, 2019). "Observations reporting consistent TRPV4 down-regulation during diabetes challenge this view." (PMID 29026201, 2017). "Our results provide important insights into the pathogenesis of diabetic retinopathy that will further guide us toward rationally-guided new therapies: synergistic combination of selective TRPV4 blockers and vasoinhibins can be proposed to mitigate diabetes-evoked BRB breakdown." (PMID 29026201, 2017). "Taken together with the fact that BRB breakdown is a feature of diabetes, this information prompted us to examine whether TRPV4 inhibition would eliminate the excessive increase in BRB permeability induced by a diabetic metabolic situation." (PMID 29026201, 2017). "This does not contradict that these same signals induce an exacerbated response under pathological conditions like diabetes, due to alterations in their whole signaling pathway and in the amount and/or nature of TRPV4 endogenous agonist(s), glycosylation levels, and basal levels of Ca2+ 95–97." (PMID 29026201, 2017). "Furthermore, we show that the molecular and protein expression of endothelial TRPV4 channels is decreased in the retinal microvasculature after 3-months’ experimental diabetes in rats." (PMID 26047504, 2015). "It remains, however, not known whether oxidants and the [Ca2+]i amount caused by TRPV4 activation interact in the DRGs of mice suffering from diabetes mellitus." (PMID 38976129, 2024). "As previously proposed, reduced TRPV4 expression may be a compensatory effect in diabetes." (PMID 31048895, 2019). "A reduced protein expression of endothelial TRPV4 channels has also been reported in retinal arterioles and mesenteric arteries from STZ-induced diabetic rats, and as such this expression was associated with impaired EDH-mediated responses in mesenteric arteries of this diabetes rat model." (PMID 31370156, 2019). "Reduced TRPV4 expression may be a compensatory effect in diabetes." (PMID 31048895, 2019). "In summary, we have provided direct evidence of functional TRPV4 expression in the cell membrane of the retinal microvascular endothelium and demonstrated that this expression is downregulated both by hyperglycaemic culture conditions in vitro and by diabetes in vivo." (PMID 26047504, 2015).
diabetes (continued). "Using DPN measurement, oxidant, and apoptotic techniques, we were able to show that diabetes mellitus produces mechanical and thermal DPN by means of TRPV4 stimulation." (PMID 38976129, 2024). "Moreover, we found that whereas oxidative damage and apoptosis generated in DRGs target TRPV4 to produce DPN, RESV reduced DPN, oxidative neuro-injury, and apoptosis via the modulation of TRPV4 in the DRG of mice with diabetes mellitus." (PMID 38976129, 2024). "TRPV4 was genetically ablated or pharmacologically inhibited as follows: left eyes were used as vehicle control and right eyes were intravitreally injected with TRPV4-selective antagonist GSK2193874, 24 h before the end of the 4 weeks of diabetes." (PMID 31048895, 2019). "Furthermore, we have investigated a role for glucose in the regulation of TRPV4 expression and discussed the implications that these findings may have on the ability of the collecting duct to detect and respond to osmotically induced signals under pathophysiological conditions such as diabetes." (PMID 23049542, 2012).
gastric cancer (18 papers, 2016 to 2024). A primary or metastatic malignant neoplasm involving the stomach. "Additionally, in gastric cancer TRPV4 is upregulated and is even associated with higher tumor invasion, lymph node metastasis and poor survival." (PMID 34199609, 2021). "TRPV4 is overexpressed in colorectal, lung, and gastric cancer cells, but in other tumors, including prostate, skin, and esophageal cancer cells, TRPV4 channel expression appears to be normal." (PMID 37892239, 2023). "TRPV4 is also overexpressed in hepatocellular carcinoma patients with high histological grade, and TRPV4-mediated Ca2+ entry enhanced gastric cancer cell proliferation, migration and invasion." (PMID 36619170, 2022). "We and others have found that TRPV4 regulates intracellular Ca2+ levels in colon cancer, gastric cancer, and hepatocellular carcinoma." (PMID 36619170, 2022). "Xie and colleagues suggested that TRPV4 served as preventive or therapeutic strategies for human gastric cancer." (PMID 34814869, 2021). "Accordingly, in gastric cancer, TRPV4-mediated Ca2+ influx promotes cell migration through the activation of the downstream Akt/β-catenin pathways." (PMID 33132914, 2020). "Pharmacological inhibition of TRPV4 in patient-derived hepatocellular carcinoma cells leads to increased apoptosis and in gastric cancer, TRPV4 activity augments oncogenic potential." (PMID 32887220, 2020). "To date, several experimental pieces of evidence have revealed a critical role of TRPV4 in regulating the migratory properties of many tumors, including liver, breast and gastric cancer." (PMID 33132914, 2020). "In gastric cancer, calcium enhanced the expression of calcium-sensitive receptor (CaSR) and targeted TRPV4 to promote metastasis." (PMID 33230171, 2020). "Studies have also shown that calcium-sensing receptor (CaSR) and TRPV4 were colocalized in gastric cancer cells, and CaSR activation evoked TRPV4-mediated Ca2+ entry promote gastric cancer cells proliferation." (PMID 31235786, 2019). "TRPV4-mediated calcium influx has been shown to be involved in the context of EMT, and hyperactivation of TRPV4 is associated with EMT in several cancer types, including breast, colorectal, and gastric cancers." (PMID 39517820, 2024). "Furthermore, the TRPV4-mediated Ca2+ pathway promotes the proliferation, migration and invasion of gastric cancer cells." (PMID 36619170, 2022). "Abnormal expression of TRPV4 is closely related to tumor formation and metastasis, which is higher in gastric cancer, lung cancer, and colorectal cancer cells, but lower in esophageal cancer and prostate cancer cells than in normal tissue cells according to the researches on TRPV4." (PMID 31235786, 2019). "Ca2+ signaling is required for the carcinogenesis and progression of gastric cancer, and activation of VIPR1 by VIP can stimulate TRPV4-mediated Ca2+ entry." (PMID 36157238, 2022). "More intriguingly, in gastric cancer, VIPR1/TRPV4/Ca2+ signaling stimulates VIP secretion, enforcing a positive feedback loop in promoting cancer progression." (PMID 35864952, 2022). "Furthermore, VPAC1 and TRPV4 channels may accelerate gastric cancer progress by relying on calcium." (PMID 34336882, 2021). "Human gastric biopsy samples, a human gastric cancer cell line (AGS), and a normal gastric epithelial cell line (GES‐1) were used to detect TRPV4 mRNA and protein expression by RT‐PCR and Western blotting, respectively." (PMID 27687509, 2017). "We showed TRPV4 expression in human gastric epithelium and the noncancerous gastric epithelial cell line, GES‐1, as well as methylation‐dependent gene silencing in the human gastric cancer cell line, AGS." (PMID 27687509, 2017).
Stroke (16 papers, 2013 to 2026). Sudden impairment of blood flow to a part of the brain due to occlusion or rupture of an artery to the brain. "During the acute phase of stroke, TRPV4 activation has been linked to neuronal injury and cerebral edema." (PMID 41606676, 2026). "Our results suggest that targeting excessive TRPV4 and RhoA pathway activity may hold therapeutic promise for patients with TRPV4 mutations and in other conditions associated with TRPV4 and RhoA dysregulation, such as traumatic brain injury, stroke, and pulmonary edema." (PMID 33664271, 2021). "This review summarizes current findings on TRPV4 in stroke pathobiology and discusses its potential as a mechanotherapeutic target." (PMID 41606676, 2026). "Increased expression or activation of TRPM2, TRPV2, and TRPV4 was observed in stroke." (PMID 41399206, 2025). "Functional TRPV4 was expressed in EC of rat MCA post‐stroke." (PMID 40116175, 2025). "However, the combination of endothelium denudation and BKCa inhibition had a strong synergistic effect in inhibiting TRPV4‐induced MCA dilation after stroke." (PMID 40116175, 2025). "Therefore, inhibition of TRPM2, TRPV2, and TRPV4 channels emerges as promising anti‐neuroinflammatory targets for stroke treatment." (PMID 41399206, 2025). "Region-specific elevations of TRPV4, surrounding the site of pathology, have been reported in high-grade meningiomas, in a model of stroke (middle cerebral artery occlusion, (MCAO)) and experimental spinal cord injury (SCI), but these studies lack vascular specification." (PMID 38521959, 2024). "As Ca2+ entry via NMDARs is the major pathway leading to neuronal death following stroke, TRPV4 channel activation could aggravate glutamate excitotoxicity." (PMID 36527242, 2023). "In astrocytes, TRPV4 expression or activity was gradually enhanced post‐stroke." (PMID 36527242, 2023). "Here we analyzed whether TRPV4 inhibition has an impact on transendothelial resistance under homeostatic and inflammatory conditions and whether deletion of Trpv4 affects the clinical outcome in mouse models of multiple sclerosis and stroke." (PMID 32974355, 2020). "The pathological changes in a stroke may facilitate the activation of TRPV4 and moreover, an increased TRPV4 protein level is found during ischemia-reperfusion." (PMID 25914628, 2015). "Therefore, it is proposed that during stroke, the over- or hyper-activation of TRPV4 aggravates the increase of [Ca2+]i, helping to increase the activated MMP-9." (PMID 25914628, 2015). "Therefore, the enhancement of NMDAR response or/and increase in glutamate release is likely involved in TRPV4-mediated neuronal injury during stroke." (PMID 23459987, 2013). "Therefore, it is possible that during stroke, TRPV4 over-activation exacerbates ROS and NO production to induce neuronal injury." (PMID 23459987, 2013). "Transient receptor potential vanilloid 4 (TRPV4) can be activated by multiple stimuli that may happen during stroke." (PMID 23459987, 2013). "After a stroke, the activation of TRPV4 may occur in response to heightened intracranial pressure." (PMID 39333347, 2025). "Therefore, blocking TRPV4 might be neuroprotective post‐stroke but its clinical effect necessitates further investigation." (PMID 36527242, 2023). "Furthermore, it was previously shown that TRPV4 activation following stroke increases NMDA receptor function, which may facilitate glutamate excitotoxicity." (PMID 36568889, 2022). "Therefore, TRPV4-induced enhancement of NMDAR response may helps to facilitate glutamate-neurotoxicity during stroke." (PMID 23459987, 2013). "In addition to affecting NMDARs, Ca2+ entry via TRPV4 also stimulated the production of ROS and nitric oxide (NO), downregulated p‐Akt, and upregulated p‐ERK, thus exacerbating neuronal injury post‐stroke." (PMID 36527242, 2023).
Stroke (continued). "Given the absence of a phenotype and a difference in BBB permeability in Trpv4–/– mice subjected to EAE, we decided to investigate the effects on experimental stroke, another model with significant impact of BBB disruption on clinical outcome but with more mildly and acute inflammation." (PMID 32974355, 2020).
edema (14 papers, 2015 to 2024). An abnormal accumulation of fluid beneath the skin, or in one or more cavities of the body. "TRPV4 is implicated in neuromuscular and skeletal disorders, pulmonary edema, and cancers, and represents an important drug target." (PMID 37353478, 2023). "In the context of chlorine inhalation toxicity, both genetic and pharmacologic inhibition of TRPV4 reduced pulmonary edema and inflammation and improved pulmonary function and oxygen saturation in chlorine-exposed mice." (PMID 38612759, 2024). "As a regulator of alveolo-capillary barrier integrity, Transient Receptor Potential Vanilloid 4 (TRPV4) antagonism represents a promising strategy for reducing pulmonary edema secondary to chemical inhalation." (PMID 38612759, 2024). "It is suggested, that TRPV4-mediated Ca2+-influx into alveolar epithelial and vascular endothelial cells contributes to barrier disruption and pulmonary edema." (PMID 26973533, 2016). "Ischemic brain injury leads to brain edema via hyperthermia-induced TRPV4 activation." (PMID 33710819, 2021). "Mice lacking TRPV4 (TRPV4 KO) had less vascular leak, pulmonary edema (wet/dry ratio, filtration coefficient), and NO production in response to high volumes (peak inflation pressure 35 cm H2O) when compared to WT controls." (PMID 28523001, 2017).
epilepsy (13 papers, 2014 to 2025). A brain disorder characterized by episodes of abnormally increased neuronal discharge resulting in transient episodes of sensory or motor neurological dysfunction, or psychic dysfunction. "This basic function of TRPV4, as a translator of brain temperature information, has been implicated in several diseases, including epilepsy and stress-induced depression." (PMID 39578735, 2024). "Previous studies have shown that TRPV channels, including TRPV1 and TRPV4, are involved in epileptogenic processes, demonstrating their roles in the pathological mechanisms of epilepsy." (PMID 40708193, 2025). "Collectively, these mechanisms underscore the importance of TRPV4 in epilepsy, highlighting its potential as a therapeutic target." (PMID 39333347, 2025). "Furthermore, blocking TRPV4 downregulates NF-κB signaling, reducing inflammation and neuronal death, which are critical in the progression of epilepsy." (PMID 39333347, 2025). "Recent evidence suggests a significant link between TRPV4 and epilepsy." (PMID 39333347, 2025). "Furthermore, overexpression of NFIA in astrocytes augmented the expression of inflammatory cytokines via the functional activity of TRPV4, thus aggravating neuroinflammation and exacerbating epilepsy." (PMID 37880726, 2023). "Our recent study confirmed that TRPV4 and glial fibrillary acidic protein (GFAP) are synchronously upregulated in human hippocampal tissues from TLE patients and a 4-aminopyridine (4-AP)-induced epilepsy mice, and also explored the functional activity of TRPV4 promotes the reactivity of astrocytes." (PMID 37880726, 2023). "Pharmacological blockade of TRPV4 function may offer a potential therapy for neuronal injury following epilepsy." (PMID 31097691, 2019). "TRPV4 is indicated to be participating in epilepsy regulation." (PMID 25147437, 2014). "TRPC1, TRPC3-7, TRPM2, TRPM7, TRPV1, TRPV4, and TRPA1 have been shown to be involved in epilepsy." (PMID 33748103, 2021). "The results indicated that TRPA1, but not TRPV4, protein levels increased in the KA-induced epilepsy model." (PMID 25147437, 2014).
hepatocellular carcinoma (13 papers, 2020 to 2025). A malignant tumor that arises from hepatocytes. "The expression of TRPV4 in hepatocellular carcinoma cells is significantly up-regulated, which leads to enhanced EMT and reduced cell apoptosis." (PMID 35813831, 2022). "Yu and colleagues reported that inhibition of TRPV4 reduced malignant biological behavior of hepatocellular carcinoma." (PMID 34814869, 2021). "Additionally, antagonism of TRPV4 channels in hepatocellular carcinoma (HCC) leads to decreased ERK phosphorylation/activation, a key pathway involved in cell proliferation." (PMID 35004649, 2021). "Inhibition of TRPV4/calcium/NF-κB signaling pathway attenuates hepatic oxidative stress and inflammatory injury.The combination of TM and HAL has great potential for the treatment of hepatocellular carcinoma by reducing tumour hypoxia and angiogenesis." (PMID 40809021, 2025). "In hepatocellular carcinoma, increased TRPV4 protein and mRNA levels were found compared to paired non-tumoral liver tissue." (PMID 37240443, 2023). "Protein and mRNA levels of TRPV4 are elevated in hepatocellular carcinoma tissue compared with paired non-tumor tissue." (PMID 32182937, 2020).